TRPM2 (transient receptor potential cation channel subfamily M member 2)
Diseases named in the same sentence as TRPM2 in open-access papers (continued):
Sharing a sentence is not in itself a finding about the gene and the disease.
lung carcinoma (9 papers, 2016 to 2026). "Consistent with our study, F. Morandi concluded that inactivation of the CD38-cADPR axis might serve as a novel therapeutic intervention in lung cancer and a recent report indicated that TRPM2 was linked with poor prognosis in patients with pancreatic ductal adenocarcinoma." (PMID 34226519, 2021). "In addition, TRPM2 downregulation inhibited the tumor growth of lung cancer in a xenograft NOD/SCID mouse model." (PMID 35071322, 2021). "In addition, a high expression of TRPM2 was closely associated with poor prognosis in bladder, head and neck, liver, and lung cancers (adenocarcinoma) (OR = 14.260–389.563), implying that TRPM2 significantly affects cancer progression." (PMID 35071322, 2021).
Obesity (9 papers, 2016 to 2025). Accumulation of substantial excess body fat. "Such deficient vasorelaxation was in part rescued by treatment of aorta with ACA, suggesting a role for the TRPM2 channel in obesity-associated endothelial insulin resistance." (PMID 34063677, 2021). "Interestingly, TRPM2-deficient mice were protected from developing diet-induced obesity and insulin resistance when fed a HFD." (PMID 41009007, 2025). "Experimental disease models have shown that preventing TRPM2 channel activation mitigates many conditions, including diabetes, obesity, hypertension, atherosclerosis, ischemia/reperfusion (I/R) injury, heart failure, and endothelial dysfunction." (PMID 40867637, 2025). "The discovery of the signalling events (mediated by NOX-2, TRPM2 and Zn2+) upstream of Drp-1 thus promises new therapeutic opportunities for obesity-induced T2D." (PMID 28753206, 2017). "Similarly, exposure of pancreatic β-cells to free fatty acids (obesity stress) leads to TRPM2-dependent organelle damage and cell death." (PMID 40867637, 2025). "Among the TRP family, certain members, such as transient receptor potential canonical 1 (TRPC1), transient receptor potential canonical 6 (TRPC6), and transient receptor potential melastatin 2 (TRPM2), have been implicated in obesity, oxidative stress, and kidney diseases." (PMID 41009007, 2025). "TRPM2 agonists may represent new pharmacological strategies to fight obesity." (PMID 38390373, 2023). "In addition, mice lacking TRPM2 displayed protection to diet-induced obesity, that was explained by a higher energy expenditure and a lower adipose tissue inflammation in Trpm2-/- compared to wild type (WT) controls." (PMID 38390373, 2023).
pancreatic cancer (9 papers, 2018 to 2023). "A link between SIRT6 and Ca2+ homeostasis, involving TRPM2 channels, had been previously demonstrated in pancreatic cancer cells, but a correlation between SIRT6 and the ATP/P2X/Ca2+ pathway has not been highlighted yet." (PMID 37047732, 2023). "The BxPC-3 cell model also demonstrated TRPM2 overexpressing was closely related to PKC/MEK pathway in pancreatic cancer." (PMID 34099637, 2021). "The nude mice tumor-bearing model results in this article is another evidence that support TRPM2’s promotion effect in pancreatic cancer." (PMID 34099637, 2021). "We found that TRPM2 was significantly higher expressed in human pancreatic cancer tissue than in para-tumor tissue in both mRNA level and protein level." (PMID 34099637, 2021). "Here, we designed new experiments to investigate the role and mechanism of TRPM2 in pancreatic cancer." (PMID 34099637, 2021). "We analyzed the mechanism of TRPM2 in pancreatic cancer by transcriptome analysis, western blot, and PCR." (PMID 34099637, 2021). "The progression-free survival (PFS) period also significantly shortened as the TNM stage (Pearson’s coefficient = −0.89) and TRPM2 level (Pearson’s coefficient = −0.85) increased in pancreatic cancer patients." (PMID 34099637, 2021). "We blocked the downstream PKC/MEK pathway of TRPM2 to investigate the mechanism of TRPM2 in pancreatic cancer by CCK8, scratch wound healing, and transwell assays." (PMID 34099637, 2021). "TRPM2 overexpressed and siRNA plasmid were created and transfected with pancreatic cancer cell line (BxPC-3) to construct the cell model." (PMID 34099637, 2021). "We employed CCK-8, Transwell, scratch wound, and nude mice tumor-bearing model to investigate the role of TRPM2 in pancreatic cancer." (PMID 34099637, 2021). "TRPM2 promotes pancreatic cancer through the PKC/MAPK pathway." (PMID 35783291, 2022). "In our last report, TRPM2 plays a promising role in pancreatic cancer." (PMID 34099637, 2021). "It showed that TRPM2 increased the invasiveness of BxPC-3 pancreatic cancer cells." (PMID 34099637, 2021). "This study was designed to investigate the role and mechanism of TRPM2 in pancreatic cancer." (PMID 34099637, 2021). "This indicates that TRPM2 has a proliferation-promoting effect on BxPC-3 pancreatic cancer cells." (PMID 34099637, 2021). "An analysis performed by Lin and colleagues revealed that somatic mutations in the TRPM2 gene exhibit a negative correlation with pancreatic cancer patient survival rates in comparison to the group without TRPM2 mutations." (PMID 32182937, 2020). "The TRPM2 may promote pancreatic cancer through PKC/MEK pathways." (PMID 34099637, 2021). "It showed that TRPM2 could promote migration of BxPC-3 pancreatic cancer cells." (PMID 34099637, 2021). "TRPM2 and 7 are overexpressed in humans while TRPM8 is reported overexpressed in pancreatic cancer cell lines." (PMID 33925979, 2021). "In 2010, much like TRPM7 and TRPM2, TRPM8 was reported to be overexpressed in pancreatic cancer cell lines (PANC-1 and BxPC-3) when compared to pancreatic ductal epithelia." (PMID 33925979, 2021). "TRPM2 expression was also shown to enhance proliferation, migration, and invasion of PANC-1 cells, a human pancreatic cancer cell line." (PMID 32182937, 2020). "Plus the results in this article, we have demonstrated that TRPM2 could promote proliferation and invasion ability in vitro in both PANC-1 and BxPC-3 pancreatic cancer cell lines." (PMID 34099637, 2021). "The level of TRPM2 also increased as the patients’ TNM stage increased, meanwhile, the patients’ overall survival (OS) period significantly shortened as the TNM stage (Pearson’s coefficient = −0.92) and TRPM2 level (Pearson’s coefficient = −0.88) increased in pancreatic cancer patients." (PMID 34099637, 2021). "Overexpressed TRPM2 could promote pancreatic cancer in proliferation, migration, and invasion ability in no matter the cell model or nude mice tumor-bearing model." (PMID 34099637, 2021).
Parkinson disease (9 papers, 2011 to 2025). A progressive degenerative disorder of the central nervous system characterized by loss of dopamine producing neurons in the substantia nigra and the presence of Lewy bodies in the substantia nigra and locus coeruleus. "Given that an increase in burst firing in SNr GABAergic neurons is observed in Parkinson’s disease and that oxidative stress is linked to Parkinson’s disease, TRPM2 could be associated with the pathophysiology of Parkinson’s disease." (PMID 33644051, 2021). "Based on its response to oxidative stress, the activation of TRPM2 channel mediates several neurodegenerative diseases, including Alzheimer’s disease, Parkinson’s disease, multiple sclerosis, and stroke." (PMID 36353687, 2022). "Additionally, excessive activation of TRPM2 in neurons may also be associated with the development of long-term depression (LTD) and Parkinson’s disease (PD)." (PMID 39007141, 2024). "Accordingly, whether TRPM2 currents are enhanced in models of Parkinson's disease (or other neurodegenerative disease in which GSH is depleted) and whether knock-out of TRPM2 may attenuate neurodegeneration has yet to be investigated." (PMID 22487454, 2012).
Cognitive impairment (8 papers, 2019 to 2024). Abnormal cognition is characterized by deficits in thinking, reasoning, or remembering. "Pharmacological inhibition of TRPM2 reduced hyperglycemia-induced cognitive impairment by down-regulating calcium-related downstream signaling in rats." (PMID 38308007, 2024). "This work aimed to assess Pur’s effects on BCCAO-induced VD and to dissect the underlying mechanisms, especially examining the function of transient receptor potential melastatin-related 2 (TRPM2) in alleviating cognitive deficits and vascular injuries." (PMID 34720898, 2021). "TRPM2 knockout improved central nervous system inflammation and cognitive impairment by inhibiting the activation of microglia in a mouse model of chronic cerebral hypoperfusion with bilateral common carotid artery stenosis." (PMID 34845114, 2021). "For example, selective deletion of the TRPM2 expression in peripheral immune cells substantially protected infarction and cognitive impairment in mice after transient MCAO and reperfusion." (PMID 30914955, 2019). "In this context, we have previously reported that TRPM2, which is a ROS-sensitive TRP channel and functionally expressed in microglia, aggravates CNS inflammation, white matter injury, and cognitive impairment in the middle to late stages of BCAS-induced VCI." (PMID 37478173, 2023). "In this study, we found that the down regulation of TRPM2 and up regulation of NR2B regulated by PAE can significantly reduce the calcium concentration in the injured neurons and improve the cognitive impairment of vascular dementia rats." (PMID 34903262, 2021). "A major limitation of this study is that we did not reveal the mechanism underlying how PAE decreases TRPM2 and increases NR2B protein levels to prevent cognitive impairment of vascular dementia rats." (PMID 34903262, 2021). "Collectively, these results therefore support a critical role for the TRPM2 channel in mediating microglial cell activation and generation of proinflammatory cytokines, IL-1β, TNF-α and IL-6, in the aggravation of cognitive impairment by chronic cerebral hypo-perfusion." (PMID 30914955, 2019).
Hyperglycemia (7 papers, 2016 to 2024). An increased concentration of glucose in the blood. "Thus, TRPM2 may represent a new target for ameliorating T2DM caused by hyperglycemia-induced oxidative stress and subsequent NLRP3 inflammasome activation." (PMID 36378463, 2023). "Selenium and resveratrol improved hyperglycemia-induced oxidative retinopathy and optic nerve apoptosis by the down-regulation of TRPM2 activity in mice." (PMID 38308007, 2024). "TRPM2-mediated Ca2+ influx derived from hyperglycemia-induced ROS triggered lysosomal membrane permeabilization and Zn2+-mediated mitochondrial fission in HUVECs." (PMID 38308007, 2024). "Melatonin and selenium reduced hyperglycemia-induced excessive ROS release, apoptosis, and Ca2+ influx through inhibiting TRPM2 and TRPV1 channel activation in dorsal root ganglion and hippocampus of diabetic rats." (PMID 38308007, 2024). "TRPM2 knockdown attenuates hyperglycemia-induced myocardial apoptosis and promotes autophagy in HFD/STZ-induced diabetic mice or HG-stimulated cardiomyocytes via regulating the MEK/ERK and mTORC1 signaling pathway." (PMID 38308007, 2024). "The genetic ablation of Ca2+-permeable non-selective cation channel TRPM2 results in defective insulin secretion in CD1 mice; consequently, TRPM2 KO mice fed a high-glucose diet develop hyperglycemia due to insufficient insulin release." (PMID 36674711, 2023). "In conclusion, we demonstrated that TRPM2 was a Ca2+ mediator of hyperglycemia-induced ROS production and NLRP3 inflammasome activation through cooperatively interaction with p47 phox, and regulation of TXNIP in human monocytes." (PMID 27731349, 2016). "To explore whether TRPM2 knockdown improved DCM under the state of hyperglycemia, we knocked down TRPM2 expression with by a single caudal vein injection of ~ 1 × 1011 genome copies of recombinant AAV9-U6-shTRPM2 at 6 weeks of age." (PMID 38308007, 2024). "Hyperglycemia-induced inflammation and fibrosis could be inhibited by TRPM2 silencing through the inhibition of JNK1 activation in vivo and in vitro." (PMID 34845114, 2021). "In this study, we used a hyperglycemia model in U937 monocytes, and identified that TRPM2 could serve as a glucose sensor." (PMID 27731349, 2016). "Moreover, we used a hyperglycemia model in U937 monocytes, showing that the activation of TRPM2 was augmented, and TRPM2-mediated Ca2+ influx was critical for NLRP3 inflammasome activation." (PMID 27731349, 2016). "To determine whether hyperglycemia altered TRPM2 function, we first treated U937 monocytes with various glucose concentrations for different timepoints." (PMID 27731349, 2016). "Therefore, our results supported that TRPM2 represented a potential therapeutic target for ameliorating NLRP3 inflammasome activation related to hyperglycemia-induced oxidative stress in T2DM." (PMID 27731349, 2016). "Long-term hyperglycemia environment-induced oxidative stress contributed to the pathogenesis and progression of T2DM20, however the role of TRPM2 under HG condition is still unknown." (PMID 27731349, 2016).
Hypertension (7 papers, 2014 to 2026). The presence of chronic increased pressure in the systemic arterial system. "In summary, TRPM2-mediated Ca2+ signaling aggregates the dysfunction of endothelial cells and vascular smooth muscle cells in the development and progression of hypertension." (PMID 35159300, 2022). "In a recent study, the Ca2+ dysregulation and hyperactivity of vascular smooth muscle cells during hypertension was found to be dependent on TRPM2-mediated Ca2+ influx, which is activated by angiotensin-II-mediated increase of ROS production." (PMID 35159300, 2022). "Examples of ion channel-annotated genes derived from the DBP phenotype include TRPM2 (cation channel), SCN11A (sodium ion channel), ITPR1 (Ca+2-release mediator), and, (implicated in hypertension." (PMID 25519358, 2014). "As a cellular sensor for oxidative stress, TRPM2 might mediate the detrimental effects of ROS on endothelial cells and smooth muscle cells in the development of hypertension." (PMID 35159300, 2022). "Furthermore, TRPM2 inhibition ameliorated experimentally induced hypertension." (PMID 40867637, 2025). "Moreover, pharmacological TRPM2 inhibition was shown to improve insulin sensitivity in adipose tissue during angiotensin II-induced hypertension, suggesting that targeting TRPM2 may be a novel therapeutic strategy to treat hypertension-associated insulin resistance." (PMID 38390373, 2023). "From a translational standpoint, approaches that enhance TRPM2-dependent signaling in atrial cells or otherwise amplify the ANP axis could help boost ANP output and mitigate pathological remodeling in heart failure or hypertension." (PMID 41511308, 2025).
Insulin resistance (7 papers, 2021 to 2025). Increased resistance towards insulin, that is, diminished effectiveness of insulin in reducing blood glucose levels. "A recent study has investigated the role of the TRPM2 channel in mediating obese-associated endothelial insulin resistance." (PMID 34063677, 2021). "The involvement of TRPs in insulin resistance first remits to TRPC4 and TRPM2, as their activation leads to pancreatic cell depolarization and Ca2+ influx, thus regulating insulin secretion by distinct mechanisms." (PMID 35455971, 2022). "For instance, TRPM2 is another TRP activated by ROS (specifically, H2O2), which is involved in insulin resistance." (PMID 35455971, 2022).
leukemia (7 papers, 2016 to 2023). A malignant (clonal) hematologic disorder, involving hematopoietic stem cells and characterized by the presence of primitive or atypical myeloid or lymphoid cells in the bone marrow and the blood. "To begin to generalize our results to other cancers, we studied U937 leukemia cells with TRPM2 deletion." (PMID 35428820, 2022). "Viability of leukemia cells with TRPM2 deletion was reduced after doxorubicin treatment compared to control and the magnitude of the relative reduction increased with time of doxorubicin exposure." (PMID 35428820, 2022). "In fact, mice injected with TRPM2-depleted leukaemia cells showed significantly reduced leukaemia, compared to controls, suggesting that these channels play an important role in leukemogenesis." (PMID 34065398, 2021). "Mice injected with TRPM2-depleted cells demonstrated significantly reduced leukemia compared with scrambled controls in three experiments." (PMID 32312983, 2020). "In in vitro experiments and in xenografts, depletion of TRPM2 in AML inhibited leukemia proliferation, and doxorubicin sensitivity was increased." (PMID 32312983, 2020). "In TRPM2-depleted leukemia cells, expression of IQGAP1 is decreased, contributing to reduced Nrf2 stability." (PMID 32312983, 2020). "A major finding of this report is that Nrf2 is significantly reduced in TRPM2 depletion in leukemia, contributing to increased ROS and chemotherapy sensitivity." (PMID 32312983, 2020). "Decrease in transcription factors including HIF-1/2α, FOXO3a, and CREB in TRPM2-depleted leukemia cells, a third finding of this report, contributes to ETC dysfunction through reduced ETC protein expression, increasing mitochondrial ROS and reducing ATP." (PMID 32312983, 2020). "Because mitochondria are dysfunctional in TRPM2-depleted leukemia cells and ROS levels are increased, the effect of TRPM2 depletion on autophagy was examined." (PMID 32312983, 2020). "The ULK1 promoter has several putative CREB sites, and CREB is downregulated in TRPM2-depleted leukemia cells." (PMID 32312983, 2020). "Atg13 and FIP200 are reduced in TRPM2-depleted leukemia cells, and this may contribute to reduced ULK1 stability." (PMID 32312983, 2020). "Indeed, TRPM2 depletion significantly inhibited human leukemia proliferation and increased leukemia sensitivity to doxorubicin." (PMID 32312983, 2020). "Expression of HIF-1α and HIF-2α, which are regulated by calcium dependent pathways and involved in modulation of mitochondrial proteins including members of the ETC, were decreased in TRPM2-depleted U937 leukemia cells, as was the downstream transcription factor FOXO3a." (PMID 32312983, 2020). "In AML cells, the transient receptor potential melastatin 2 (TRPM2) ion channel displayed high expression compared to CD34+ healthy precursor cells, and its suppression inhibited the proliferation of leukemia cells." (PMID 35159351, 2022). "In this regard, integrated methylome, transcriptome, and epigenetic analysis showed that the expression level of many genes is dysregulated in paediatric leukaemia, and among them, the presence of TRPC1, TRPC4, TRPC3, TRPM2, TRPM4, and TRPM8 also stands out." (PMID 34065398, 2021). "The first major finding of this report is that TRPM2 expression is increased in leukemia cells of patients with AML, suggesting TRPM2 is pro-survival." (PMID 32312983, 2020).
amyotrophic lateral sclerosis (6 papers, 2011 to 2025). Amyotrophic lateral sclerosis (ALS) is a neurodegenerative disease characterized by progressive muscular paralysis reflecting degeneration of motor neurons in the primary motor cortex, corticospinal tracts, brainstem and spinal cord. "Loss of function mutations in TRPM7 and TRPM2 have been associated with Western Pacific Amyotrophic Lateral Sclerosis (ALS) and Parkinsonism Dementia (PD)." (PMID 33853504, 2021). "In a subset of Guamanian amyotrophic lateral sclerosis and Parkinson dementia patients, a TRPM2 mutant (P1018L) was found which inactivates after channel opening, limiting Ca2+ entry and supporting the conclusion that TRPM2 is necessary for normal neuronal function." (PMID 31575956, 2019). "Alterations in TRPM2 channel expression and function have also been demonstrated in other chronic diseases, such as Western Pacific amyotrophic lateral sclerosis (ALS) and PD." (PMID 30037128, 2018).